POC5 (POC5 centriolar protein)
Description:
Essential for the assembly of the distal half of centrioles, required for centriole elongation. Acts as a negative regulator of centriole elongation.
Synonyms: hPOC5; C5orf37; FLJ35779; MGC120442; MGC120443; MGC120444
Tractability: PROTAC: ubiquitination databases record sites on it; its protein half-life has been measured.
Gene: Protein-coding gene on chromosome 5 (75,674,124 to 75,717,448, reverse strand). Ensembl gene ENSG00000152359.
Subcellular location: Cytoplasm, cytoskeleton, microtubule organizing center, centrosome; Cytoplasm, cytoskeleton, microtubule organizing center, centrosome, centriole
Gene Ontology:
Molecular function: protein binding
Biological process: centriole elongation; negative regulation of centriole elongation; eye photoreceptor cell development
Cellular component: centriole; centrosome; photoreceptor connecting cilium
Genetic constraint (gnomAD): Loss-of-function variants: 34 observed, 45.49 expected, observed/expected ratio (o/e) 0.75, 90% interval 0.57 to 1. The upper end of that interval is the gene's LOEUF score, 1, which puts it in group 4 of 6, group 1 being the genes least tolerant of losing a copy. Missense variants: 605 observed, 583.39 expected, observed/expected ratio (o/e) 1.04, 90% interval 0.97 to 1.11. Synonymous variants: 211 observed, 201.02 expected, observed/expected ratio (o/e) 1.05, 90% interval 0.94 to 1.18.
Homologues: Orthologues: chimpanzee POC5 (99% identical), macaque POC5 (97% identical), dog POC5 (86% identical), pig POC5 (83% identical), guinea pig POC5 (81% identical), rabbit POC5 (77% identical), mouse Poc5 (76% identical), rat Poc5 (72% identical).
Diseases named in the same sentence as POC5 in open-access papers:
POC5 is named in the same sentence as 28 diseases in open-access papers, as found by Europe PMC text mining. Sharing a sentence is not in itself a finding about the gene and the disease. The quoted sentences say what the papers report.
Obesity (6 papers, 2015 to 2025). Accumulation of substantial excess body fat. "GWAS studies revealed that the POC5 variant is associated with pediatric-onset type 2 diabetes risk and the association between smoking and obesity susceptibility." (PMID 40869120, 2025). "These variants mapped to well-established obesity-related genes and loci, such as POC5, MC4R, TMEM18, and the FTO locus." (PMID 38200577, 2024). "The protein encoded by POC5 is a component of cilium/centriole; therefore, it remains to be investigated how this protein contributes to obesity through lipids." (PMID 37274792, 2023). "I found as cg00601450 site becomes methylated, the expression of POC5 increases (Β = 0.15, P = 3e−81) and this leads to higher levels of lipids and obesity (β = 0.01, P = 8e−12)." (PMID 37274792, 2023). "POC5, ILRUN, FDFT1, and NEIL2 mediated the impact of CpG sites on obesity through metabolic pathways." (PMID 37274792, 2023). "Integration of methylation data with gene expression profiles revealed putative mediators of these relationships—genes such as ILRUN, POC5, FDFT1, NEIL2, and others—whose methylation changes may affect metabolic pathways and contribute to obesity pathogenesis." (PMID 41303351, 2025).
scoliosis (6 papers, 2017 to 2025). A congenital or acquired spinal deformity characterized by lateral curvature of the spine. "Variants in the centriolar protein POC5 have been associated with scoliosis through human and animal studies." (PMID 34208743, 2021). "POC5 genetically contribute to the scoliosis predisposition and is an etiological factor in scoliosis initiation, while the suggested resistance mechanism to E2 treatment could be a factor that contributes to the curve aggravation." (PMID 37239471, 2023). "To date, multiple zebrafish genetic mutants (e.g., ptk7, POC5, kif6) have linked genes involved in cilia and ciliary motility to a progressive scoliosis, giving potential insight into molecular mechanisms that may regulate scoliosis development." (PMID 37239418, 2023). "Collectively, these findings suggest that estrogen is an etiological factor in scoliosis through the deregulation of POC5." (PMID 37239471, 2023). "Although this recent case-control study reported that a common variant (rs6892146) of POC5 was associated with susceptibility to AIS, this study also shows significantly higher mRNA expression of POC5 in the muscles of patients with scoliosis compared to the controls." (PMID 37239471, 2023). "To investigate the impact of the A429V mutation and the role of POC5 in the differentiation and function of primary osteoblasts derived from healthy donors without scoliosis and AIS patients, we performed alizarin red staining, alkaline phosphatase, and Western blot analyses of COL1A2." (PMID 37239471, 2023). "Among the genes that have been confirmed to be involved in the development of scoliosis in humans (TBX6, FGF3, LBX1, POC5, TTLL1) and vertebrates (Kif6 and Ptk), several are ciliary genes." (PMID 37239471, 2023).
idiopathic scoliosis (5 papers, 2017 to 2025). A scoliosis with no known cause. "Human POC5 dysfunction is associated with idiopathic scoliosis, being hPOC5 a protein that binds centrin and that is important for centriole duplication together with Centrin and hSFI1." (PMID 30687396, 2018). "Heterozygous variants in POC5 have previously been linked to idiopathic scoliosis." (PMID 40590205, 2025). "Moreover, the POC5 mutation is associated with the susceptibility to adolescent idiopathic scoliosis and has been shown to disrupt cell cycles, alter cilia length, and affect interactions among centrosome proteins." (PMID 40869120, 2025). "Since the identification of POC5 as a candidate gene for adolescent idiopathic scoliosis and its functional validation, we have analyzed the prevalence of POC5 coding variants within the AIS population, and also have sought to identify new candidate genes." (PMID 34356048, 2021). "The POC5 gene was identified as one of the first ciliary candidate genes for AIS, as three variants were identified in large families with multiple members affected with idiopathic scoliosis." (PMID 34356048, 2021).
retinitis pigmentosa (3 papers, 2019 to 2025). Retinitis pigmentosa (RP) is an inherited retinal dystrophy leading to progressive loss of the photoreceptors and retinal pigment epithelium and resulting in blindness usually after several decades. "In addition to the association of POC5 with AIS, recently, new mutations in POC5 gene were associated with Retinitis Pigmentosa (RP)." (PMID 30845169, 2019).
adolescent idiopathic scoliosis (2 papers, 2019 to 2023). A scoliosis with no known cause arising in adolescent. "Mutations in POC5 have been identified in adolescent idiopathic scoliosis (AIS); in vitro studies of these mutations have shown that they alter centrosome protein interactions, induce ciliary retraction, and impair cell-cycle progression." (PMID 37296840, 2023).
breast carcinoma (2 papers, 2023). "There is evidence that the POC5 protein is involved in breast cancer cell proliferation and tumorigenesis." (PMID 37296840, 2023).
migraine (2 papers, 2020 to 2022). "ANKDD1B and SERPINA1 were the nearest genes to a genome-wide significant migraine risk SNP, and POC5 was the nearest gene to a genome-wide significant T2D risk SNP." (PMID 36292730, 2022). "The remaining three genes are located at two loci not previously identified for migraine (POC5 and ANKDD1B on chromosome 5q13.3, and TMEM91 on chromosome 19q13.2), thus, representing novel loci for migraine risks." (PMID 32121467, 2020).
asthma (1 paper, 2025). "The discovery of the missense variants rs13107325 and rs2307111 in SLC39A8 and POC5, respectively, in addition to other intronic and synonymous SNPs suggests that these SNPs may have some roles in the development or progression of asthma and COPD." (PMID 40869120, 2025). "The identification of missense variants, rs13107325 and rs2307111 in SLC39A8 and POC5, respectively, suggests that these genes may have some associations or roles in the development of CRDs, including asthma and COPD." (PMID 40869120, 2025). "Further analysis suggests that variants in POC5 and SLC39A8 may contribute to the observed associations between BMI and body fat percentage, and asthma and COPD." (PMID 40869120, 2025).
Azoospermia (1 paper, 2025). Absence of any measurable level of sperm,whereby spermatozoa cannot be observed even after centrifugation of the semen pellet. "Consequently, Poc5 KO mice exhibited azoospermia and male infertility." (PMID 41337589, 2025).
ciliopathies (1 paper, 2025). "This underscores the pleiotropic effects of POC5 variants and highlights the significance of adipose tissue and metabolic dysfunction in ciliopathies." (PMID 40590205, 2025). "Moreover, we show aberrant localization of POC5 at the basal body of the cilium, providing evidence that the described syndrome is a ciliopathy." (PMID 40590205, 2025).
cancer (2 papers, 2023 to 2025). A tumor composed of atypical neoplastic, often pleomorphic cells that invade other tissues. "For instance, HDAC3 can protect proteins like POC5 (POC5 centriolar protein), which supports cancer cell proliferation, from degradation." (PMID 40006729, 2025). "A study of histone deacetylases, dysregulation of which can result in carcinogenesis, showed that one mechanism of histone deacetylase action in cancer is to protect POC5 from degradation, resulting in cell cycle progression of cancer cells." (PMID 37296840, 2023).
tumor (1 paper, 2025). "When comparing tumor tissues to standard controls, a substantial upregulation of four genes was observed: CENPQ, YAE1, FANCF, and POC5." (PMID 41502527, 2025).
POC5 also shares sentences with these, for which no sentence is quoted: type 2 diabetes (2 papers); alopecia (1); Alström syndrome (1); chronic lung disease (1); glomerulonephritis (1); hypotrichosis (1); Insulin resistance (1); lung carcinoma (1); male infertility (1); microcephaly (1); night blindness (1); nonalcoholic fatty liver disease (1); onychodysplasia (1); polycystic ovarian syndrome (1); retinal disorder (1); Retinal dystrophy (1).